TNF (tumor necrosis factor)
Diseases named in the same sentence as TNF in open-access papers (continued):
Sharing a sentence is not in itself a finding about the gene and the disease.
diabetes (continued). "Similarly, our previous study showed that after phytohemagglutinin stimulation, the PBMCs of patients with diabetes expressed lower IFNγ and IL-10 levels; however, they had higher monocyte responsiveness, which is measured based on TNFα/IFNγ and IL-6/IFNγ ratios." (PMID 39062154, 2024). "Tumor necrosis factor-alpha (TNF-α) has a pivotal role in the pathogenesis and prognosis of cancer as well as diabetes mellitus (DM)." (PMID 38406163, 2024). "However, unlike normal acute wounds, there is a large number of M1 phenotype macrophages in chronic wounds of diabetes, and these macrophages excessively produce related pro-inflammatory cytokines such as tumor necrosis factor α (TNF-α), interleukin-6 and IL-1β." (PMID 38675654, 2024). "Thus, the interaction between CXCR1/2 and TNF-α signaling pathways may contribute to the dysregulation of insulin sensitivity and the pathogenesis of diabetes." (PMID 39627194, 2024). "Abroma august is widely utilized in the treatment of diabetes and its complications in reducing vascular inflammation, hyperglycemia, and oxidative stress, with its extract negatively regulating the expression of IL-1β, NF-κB, IL-6, and TNF-α, suggesting its capacity as a nephroprotective agent." (PMID 38498532, 2024). "This comprehensive analysis for lncRNAs m6A modification in high glucose and TNF-α-induced human umbilical vein endothelial cells not only demonstrated the understanding of characteristics of endothelial cell dysfunction, but also provided the new targets for the clinical treatment of diabetes." (PMID 36897718, 2023). "In finding an association between the pathogenesis of diabetes-induced LEAD and the AGEs/ET-1/TNF-α/NOS axis, we evaluated the correlation between the score of tunica intima damage and the tissue and blood levels of AGEs, ET-1, TNF-α, NOS, TG, HDL-C, and HbA1c." (PMID 36830898, 2023). "However, we find that although composition and overall global transcriptional pattern is similar regardless of HIV serostatus, diabetic PWH have greater contribution of inflammatory signaling pathways such as IL6, IFN-γ, and TNF compared with HIV-negative persons with diabetes." (PMID 37711619, 2023). "In addition, diabetic lipocalin-2 KO mice show diminished STZ-induced Iba1 overexpression by microglia, limited macrophage infiltration and decreased pro-inflammatory cytokines expression including TNF-α and IL-6, supporting a role for lipocalin-2 in diabetes-induced brain inflammation." (PMID 36869375, 2023). "miR-204 upregulation, reduced NOX, RAGE, MMPs expression, downregulation of IKKβ/NF-κB phosphorylation, Nrf2, AdipoR1/2, JNK activation, TNF-α and IL-6, reduced macrophage infiltration, and ERK and PDX1 activation may reduce diabetes-associated CVDs and diabetic nephropathy." (PMID 37108833, 2023). "According to epidemiology, patients with diabetes mellitus (DM), hypertension, atherosclerosis, and cardiovascular events had increased levels of IL-6 and TNF-a." (PMID 37522129, 2023). "In addition, expression levels of IL-1β and TNF-α in the endplate were assessed, and it was found that levels of IL-1β (control vs diabetes: 8.158 vs 15.13; p < 0.0001) and TNF-α (control vs diabetes: 104.6 vs 131.7; p < 0.0001) in the diabetic group were increased to various degrees." (PMID 36816302, 2023). "Here in this study, we found that diabetes likely affected the phenotype of macrophages in such a delicate manner, since diabetes seemed to alter the levels of markers for macrophage functionality, iNOS, TNFα and IFNγ, and the levels of PCNA, a cell proliferation marker." (PMID 36405726, 2022). "Since oxidative stress and inflammation in the rat model of diabetes caused by streptozotocin have an important role in the progress of diabetic nephropathy, so it is necessary to evaluate several oxidative stress and inflammatory cytokine parameters such as MDA, SOD, GPx, IL-6, and TNF-α." (PMID 35685736, 2022).
diabetes (continued). "In individuals suffering from type 2 diabetes mellitus, however, the balance is tilted towards the proinflammatory side, manifested by an upregulation of proinflammatory intracellular pathways and an elevation in circulating inflammatory markers, such as C-reactive protein, IL-6, and TNFα." (PMID 35163309, 2022). "In an STZ-induced diabetic mouse trauma model, melatonin-pretreated exosomes derived from mesenchymal stem cells (MT-Exo) effectively inhibited the pro-inflammatory factors IL-1β and TNF-α, while the relative expression of anti-inflammatory factor IL-10 was increased." (PMID 36601058, 2022). "Interestingly, the correlation analysis of gut microbiota with diabetes-induced intestinal inflammation showed that Deferribacteres were positively related to FBG, pro-inflammatory cytokines such as TNF-α, IL-1β, IL-6, and IL-17, which were negatively associated with IL-10 and TGF-β." (PMID 36045662, 2022). "Additionally, from the reports obtained, we could extract the CRP and TNF-α in different races to investigate if there is an impact of demographic changes on CRP levels at the pre-diabetes stage." (PMID 36595749, 2022). "Interestingly, a systematic review assessing the effect of periodontal therapy on serum levels of inflammatory markers in people with type 2 diabetes mellitus concluded that periodontal therapy reduces serum levels of tumor necrosis factor alpha and C‐reactive protein in type 2 diabetes individuals." (PMID 35913467, 2022). "Moreover, TNF-α levels are also increased in diabetes, where it may enhance the production of inflammatory factors by T cells." (PMID 36186138, 2022). "Our research revealed that diabetes as a metabolic disease not only upregulated the expression of a broad profile of pro-inflammatory cytokines in the prefrontal cortex of mice, but it can also induce systemic inflammation accompanied by a significant increase in serum TNFα levels." (PMID 35628311, 2022). "In addition, an increase in pro-inflammatory cytokines (i.e., TNF-α and IL-6) in the circulation may trigger diabetes or atherosclerosis." (PMID 35742829, 2022). "Anti-TNF-α medicine or components may potentially prevent diabetes or prediabetes progression." (PMID 35447934, 2022). "Thus, persistent elevated TNF-α induces dysregulation of the incretin hormone, IR, and pancreatic β-cell dysfunction, which could accelerate the onset of diabetes." (PMID 35447934, 2022). "In a large retrospective cohort study conducted in patients with a diagnosis of either RA or psoriasis, the use of a TNF inhibitor (infliximab, etanercept, or adalimumab) was associated with a reduced risk of developing diabetes as compared with initiation of other nonbiologic DMARDs." (PMID 35629988, 2022). "The beneficial components of ZWD might intervene HF through the AGE-RAGE signalling pathway in the diabetes component, fluid shear stress and atherosclerosis, the TNF signalling pathway, TB, and Kaposi sarcoma related herpesvirus infection, according to a KEGG enrichment study." (PMID 35341142, 2022). "Systemic factors, such as diabetes mellitus and smoking, can contribute as modifying factors to the progression of periodontitis by increasing the release of pro-inflammatory mediators, such as interleukins (IL-1α, IL-1β and IL-6), tumor necrosis factor-alpha (TNF-α) and prostaglandins." (PMID 34413802, 2021). "In cases of systemic inflammation, such as obesity-induced diabetes, pro-inflammatory cytokines can be present in the blood and concentrated in fat tissues as activated adipose tissue macrophages (ATMs) produce tumor necrosis factor-alpha (TNF-α) and interleukin-1β (IL-1β)." (PMID 34489979, 2021). "In addition, soy protein and isoflavones may influence diabetes-related cytokines such as TNF-alpha and IL-1, then improve glucose metabolism." (PMID 34645422, 2021).
diabetes (continued). "Since P2X7 receptor is integral in the processing and release of many inflammatory mediators (IL-1β, NFκB, TNFα etc.), the inhibition of this receptor may provide therapeutic benefit in diseases including cancer, tuberculosis, diabetes, asthma, and all of the neurodegenerative diseases." (PMID 33889073, 2021). "Data from a meta-analysis reveals that T2DM (type 2 diabetes mellitus) risk as a whole was solidly correlated with increased levels of inflammatory cytokines such as interleukin (IL) 1β, IL-6, IL-18, C reactive protein (CRP) and tumor necrosis factor-α (TNF-α)." (PMID 34829612, 2021). "Aging of humans is known to be accompanied by low-grade inflammation, as manifested by consistently elevated levels of inflammatory cytokines, especially interleukin-6 (IL-6) and tumor necrosis factor-α (TNF-α); these factors could promote diverse pathologic states such as diabetes and cancer." (PMID 34948277, 2021). "In addition, AA showed potent anti-inflammatory action by virtue of its ability to suppress IL-6 and TNF-α production and the expression of NF-κB and prevented both alloxan- and streptozotocin-induced type 1 and type 2 diabetes mellitus in experimental animals." (PMID 34944517, 2021). "Additionally, OPN with other reported inflammatory cytokines particularly IL-6, IL-8, IL-18, IL-1β, TNF-α, and serum CRP have been implicated in hypertension associated with diabetes via mediating the vascular effects of both angiotensin II (Ang II) and aldosterone, respectively." (PMID 34917685, 2021). "In addition to the well-known antioxidant, anti-inflammatory, and anti-aggregation activities, it has also been shown that carnosine is able to reduce advanced glycation end products (AGEs) and tumor necrosis factor-α (TNF-α) levels in patients with type 2 diabetes mellitus (T2DM)." (PMID 33806459, 2021). "In addition, treatment with the α-glucosidase inhibitor miglitol and barley lowered the expression of inflammatory cytokines, such as interleukin 1 beta and tumor necrosis factor alpha, and integrins, such as CD11s in peripheral leukocytes of rodents with diabetes." (PMID 34867790, 2021). "Our study hypothesis is that the saliva inflammatory biomarkers will be higher in Type 2 diabetics and our study investigated the association between salivary levels of selected salivary inflammatory biomarkers (CRP, IL-6 and TNFα) in type 2 diabetes mellitus and glycaemic control." (PMID 33676486, 2021). "Therefore, the development of diabetes could reduce by administering exogenous TNF-α via an effect on the decreased production of endogenous TNF-α in NOD mice." (PMID 34572503, 2021). "The tissue damage results from increased production of TNF-α, Interleukin-1β, metalloproteases and recently, we have shown that lipid mediators, such as leukotrienes (LTB4), when produced in abundance, increases susceptibility to skin infection in experimental models of diabetes." (PMID 32525457, 2020). "Similarly, a significant increase in TNF-α levels was observed in animals with diabetes." (PMID 33072216, 2020). "Therefore, TNF-α may serve as an additional marker of diabetes and it can provide valuable information about the pathogenetic pathways and regulation of the disease process, leading to development of new immunotherapeutic strategies." (PMID 33202729, 2020). "Furthermore, we found that Alistipes was negatively correlated with TNF-α and LPS, demonstrating that Alistipes may suppress diabetic inflammation." (PMID 32028957, 2020). "Compared to the use of a much shorter time frame (1–4 h) and a high dosage of TNFα in the previous study, our findings provided insights into sustained transcriptional activation involving SE-derived caRNAs that contribute to chronic EC dysfunction in disease states, such as diabetes." (PMID 33060583, 2020).
diabetes (continued). "A study of the cytokine response demonstrated that in the mice with developed alloxan-induced diabetes, the concentrations of all measured cytokines in the plasma increased on the 10th day after the administration of alloxan, with the most marked increase observed in TNF-α and IL-5." (PMID 32908936, 2020). "In addition, circHIPK3 silencing alleviated mechanical hyperalgesia and thermal hyperalgesia in STZ-induced diabetes rats by inhibiting neuroinflammation through inhibiting the release of IL-1β, IL-6, IL-12, and TNF-α, indicating a close relationship between circHIPK3 and inflammation." (PMID 32318575, 2020). "Diabetes mellitus and AFB1 intoxication-induced oxidative stress in this study were associated with increased production of proinflammatory cytokines, IL-1β, IL-6, and TNF-α leading to hepatorenal injuries and the elevation of activities and levels of their function biomarkers." (PMID 32104544, 2020). "Pathologically, inhibition of the TNF or IL-1β pathways may benefit patients with diabetes." (PMID 31427967, 2019). "To look into the mechanism that might be attributable to the reduced thresholds of mechanical allodynia and heat hyperalgesia during the earlier phase of diabetes, we further investigated the status of TNF-α and CXCR4 protein expression over time in the DRG in addition to that in the spinal cord." (PMID 31001066, 2019). "Thus, we speculate that serum uric acid at high concentrations, when combined with other metabolic and prooxidant changes observed in diabetes, seems to enhance the proinflammatory cytokines involving IL-1, IL-6, and TNF-alpha in T2D patients." (PMID 31110596, 2019). "Both modes of infection may occur in immunocompromised patients, especially associated with human immunodeficiency virus (HIV) infection, but also diabetes mellitus, chronic alcoholism, steroids, anti-TNF treatment, hematologic cancer and transplanted patients." (PMID 30641918, 2019). "J147 reduces inflammation by decreasing TNF-α pathway activation and several other markers of neuroinflammation in mice treated with STZ, supporting that different curcumin extracts and derivates are potent antioxidants with the capability to limit associated central complications in diabetes." (PMID 31126031, 2019). "However, the deficiency of TNFα did not reduce leukostasis at earlier time points (four and six weeks of diabetes), suggesting that earlier time points were not dependent on TNFα signaling." (PMID 29301251, 2018). "Furthermore, as patients were often referred from community and other specialty clinics, ID clinic providers were often aware of medical comorbidities for e.g. HIV/AIDS, Diabetes, renal failure on dialysis, and ongoing use of TNF-α blocker use at initial clinic assessment." (PMID 30440033, 2018). "In addition, diabetes-enhanced TNF-α reduced MSC proliferation and increased MSC apoptosis." (PMID 30409193, 2018). "Furthermore, diabetes increases both hyperglycemia and serum TNF levels during endotoxemia." (PMID 29780390, 2018). "Therefore, the aim of the present study was to evaluate the possible therapeutic effects of aqueous extract of garlic on streptozotocin (STZ)+nicotinamide-induced diabetes in rats through studying TNF-α expression and oxidative stress status in the kidney tissues." (PMID 27937047, 2017). "In addition, CBD reduced elevated–TNF-α level in experimental diabetes." (PMID 28539998, 2017). "Diabetes induced a significant increase of IL-1β and TNF-α expression of Kupffer cells in STZ-DM mice as compared with the control group." (PMID 28493939, 2017). "Furthermore, adipokines and cytokines [tumor necrosis factor-α (TNF-α), interleukin-6 (IL-6), and transforming growth factor-β], induced by fat tissues in obese individuals, trigger a metabolic imbalance (IR, type 2 diabetes mellitus, etc.)by causing subclinical systemic inflammation." (PMID 28008865, 2017).
diabetes (continued). "Thus, mouse and rats’ susceptibility to develop STZ-induced type 1 DM and susceptibility of NOD and BB animals to develop diabetes is closely related to the higher levels of IL-2, IFN-γ, and TNF-α production by infiltrating macrophages and T cells and other cells." (PMID 28824543, 2017). "In addition, soft drinks contain caramel colouring which are rich in AGEs promoting inflammatory mediators that might be important in the development of diabetes, such as C-reactive protein and TNF-α." (PMID 29362720, 2017). "L-NAME but not D-NAME supplementation markedly decreased diabetes-induced IL-1β and TNF-α mRNA expression of Kupffer cells in STZ-DM mice." (PMID 28493939, 2017). "It is suggested that in the pathogenesis of PAD in patients suffering from diabetes, a significant role is played by pro-inflammatory cytokines and acute-phase proteins; the mentioned elements include interleukin-6 (IL-6), tumor necrosis factor (TNF)-alpha, C-reactive protein (CRP), and fibrinogen." (PMID 27834825, 2016). "Issues that reduce the inflammation (particularly, key inflammatory markers such as pro-inflammatory mediators TNFα, IL-6, IL-1β and CRP) could offer a vital public health tool to reduce the burden of diabetes and associated complications including cardiovascular diseases in the general population." (PMID 27527213, 2016). "Here we show that LPS stimulation leads to increased secretion of pro-inflammatory cytokines such as IL-1β and TNF-α by splenocytes and BM-derived dendritic cells enriched from diabetic mice, indicating that these immune cells may also contribute to inflammation in diabetes." (PMID 26760976, 2016). "Antioxidant supplementation by diosmin suppressed diabetes induced ROS resulting in deactivation of NF-κB associated pro-inflammatory chemokines and cytokines such as macrophage chemotactic protein (MCP-1), tumor necrosis factor (TNF-α), and interleukins (IL-1β and 6)." (PMID 27527213, 2016). "The described results propose a novel protective role of SGK-1 against apoptosis induced by ceramide and TNF-α, increasing our knowledge in this field, opening new perspectives to counteract cellular and tissue injuries, which are typical of several diseases like diabetes and its complications." (PMID 26379195, 2015). "Instead, because increased expression of TNF-α was already observed in the sham DM group, a new group was prepared which received repeated ETN doses immediately after the onset of diabetes." (PMID 26665003, 2015). "The increased TNF-α level in the serum of diabetic wounds might be due to the systemic effect of its pro-inflammatory activities in diabetes, while its locally decreased RNA expression in diabetic wounds might logically be responsible for impaired recruitment of inflammatory cells." (PMID 26498022, 2015). "Moreover, metabolic diseases, such as diabetes, also show higher TNF-α levels in the blood serum." (PMID 25485304, 2014). "Moreover, our immunohistochemistry studies also revealed that sitagliptin was able to prevent the diabetes-induced increase in IL-1β and TNF-α mainly in the cells around the glomeruli, which are probably tubular cells and/or accumulation of interstitial inflammatory cells." (PMID 24817793, 2014). "However, it has been recently illustrated that TNF-α could downregulate MSCs migration in animal model of diabetes mellitus, prompting that TNF-α may exert different roles in MSCs migration under different status." (PMID 25762184, 2014). "In conclusion, in patients with type 2 diabetes mellitus urinary, but not serum, TNF-α levels are associated with the presence and severity of microalbuminuria indicating that its intrarenal production is involved in the pathogenesis and progression of diabetic nephropathy." (PMID 25587544, 2014).